IGFBP3 (insulin like growth factor binding protein 3)
Diseases named in the same sentence as IGFBP3 in open-access papers (continued):
Sharing a sentence is not in itself a finding about the gene and the disease.
metabolic syndrome (11 papers, 2008 to 2025). A cluster of metabolic risk factors for CARDIOVASCULAR DISEASES and TYPE 2 DIABETES MELLITUS. "IGFBP-3 is associated with all five elements of the metabolic syndrome among the older population." (PMID 40538800, 2025). "The KD decreased the ratio of IGF to IGF-binding protein 3 (IGFBP3) in mouse serum, which is associated with metabolic syndrome and cancer." (PMID 36172354, 2022). "Further research will be required to more accurately elucidate the function of Angptl4, but also of Il18, Fgf15, Mif and Igfbp3 in the small intestine and their possible role in the etiology of the metabolic syndrome." (PMID 18457598, 2008). "Other potential mechanisms by which fatty liver may increase cardiovascular risk beyond that imposed by the metabolic syndrome are lipotoxicity and increased circulating IGF-1 and IGFBP-3." (PMID 23924883, 2013). "A ratio of IGF-I/IGFBP-3 may be more useful in assessing metabolic risk, as a low IGF-I/IGFBP-3 ratio is associated with an approximately 3-fold increased likelihood of having the metabolic syndrome in both men and women." (PMID 30392760, 2019).
metastatic disease (11 papers, 2001 to 2021). "In contrast to these studies, in which hypermethylation of the IGFBP3 promoter is a common and early event during tumorigenesis, we found only 9/36 of HB tumor cases to be methylated, seven of which were high-risk metastatic tumors, indicating a late event in the development of HB." (PMID 22401581, 2012). "This interpretation is consistent with the available information on the effect of IGFBP3 on ccRCC cultures: IGFBP3 blocked proliferation of a ccRCC metastatic tumor in culture and stimulated the proliferation of a primary tumor in culture." (PMID 34046336, 2021). "In contrast, the highly motile and invasive behavior of the two cell lines of metastatic tumors analyzed (Me501 and the murine line B16) was strongly inhibited by treatment with human recombinant IGFBP-3." (PMID 24905466, 2014). "Insulin like growth factor binding protein 3 (IGFBP3) is upregulated in pancreatic endocrine tumors and its overexpression is significantly more common in metastatic disease." (PMID 17181856, 2006). "Increased IGFBP-3 proteolysis was most frequently recorded in patients harbouring large tumours and metastatic disease (Stage I: 0/19, 0%; Stage II: 3/45, 7%, Stage III: 9/37, 24%, and Stage IV: 7/15, 47%)." (PMID 11437405, 2001). "In the RCC cell lines including Caki-2 (from a primary tumor) and SK-RC-52 (from a metastatic tumor) IGF-1 was shown to enhance transforming growth factor-β (TGF-β) signaling and via TGF-β raise IGF-binding protein 3 (IGFBP-3) levels with growth-promoting effect." (PMID 27405474, 2016). "In metastatic tumours IGFBP-3 staining was much weaker or absent." (PMID 24905466, 2014).
oral squamous cell carcinoma (11 papers, 2013 to 2025). "Moreover, activation of the MAPK/ERK signalling pathway in oral squamous cell carcinoma cells and breast epithelial cells has been linked to the upregulation of IGFBP3 42,43." (PMID 34512163, 2021). "In oral squamous cell carcinoma, IGFBP3 induces radiotherapy resistance through interaction with DNA-PKcs and EGFR." (PMID 41199784, 2025). "In a previous study, high IGFBP-3 expression improved the survival rate of patients with oral squamous cell carcinoma, achieved through NF- κB/IL-6/ROS signalling to promote radiosensitivity." (PMID 35069971, 2022). "PDGF-AA was shown to induce lymphangiogenesis, and IGFBP-3 was indicated to be related to lymph node metastasis in oral squamous cell carcinoma and thyroid carcinoma." (PMID 35597782, 2022). "In oral squamous-cell carcinoma, IGFBP3 mRNA expression has been correlated with a more favorable outcome, further supporting its role as an IGF1 inactivator." (PMID 23365645, 2013). "Moreover, IGFBP-3 promotes cell migration by activating β1 integrin-ERK signaling in oral squamous cell carcinoma cells." (PMID 35798794, 2022). "Ectopic insulin-like growth factor binding protein 3 (IGFBP3) expression has been shown to enhance cell migration and lymph node metastasis of oral squamous cell carcinoma (OSCC) cells." (PMID 33712045, 2021).
osteosarcoma (11 papers, 2012 to 2024). A usually aggressive malignant bone-forming mesenchymal neoplasm, predominantly affecting adolescents and young adults. "Therefore, in osteosarcoma it is proposed that miR-384 acts as a tumor suppressor through upregulation of IGFBP-3, with low expression of both associated with poor patient outcomes." (PMID 35597813, 2022). "High expression of IGFBP3 can facilitate the growth of endophytic squamous cell carcinoma cells of the tongue and stimulates human osteosarcoma cell migration." (PMID 38326861, 2024). "TRAIP enhances osteosarcoma invasion and proliferation through the modulation of IGFBP3/AKT by promoting the degradation of KANK1, which is a tumor suppressor." (PMID 36999051, 2023). "This study was interpreted as indicating that in osteosarcoma, circ-0000285 is a ceRNA which, by sponging miR-409-3p, acts as a tumor promoter, upregulating oncogenic IGFBP-3." (PMID 35597813, 2022). "In osteosarcoma cells IGFBP-3 expression has been shown to be stimulated by miR-384, resulting in decreased cell proliferation, EMT, and invasion." (PMID 35597813, 2022). "Expression of both miR-384 and IGFBP-3 was lower in osteosarcoma tissue than healthy tissue, and lowest in high-stage cancers." (PMID 35597813, 2022). "In the parallel example of osteosarcoma, high expression of circRNA circ-0000285 was found to sponge the miRNA miR-409-3p, which in turn led to upregulation of IGFBP-3." (PMID 35597813, 2022). "This research group has addressed the relationship between serum levels of IGF-1, its binding protein (IGFBP-3), and the clinical behavior and outcome of osteosarcoma in children." (PMID 22587902, 2012). "In addition, TRAIP-mediated downregulation of KANK1 can enhance the invasion and proliferation of osteosarcoma cells through the IGFBP3/AKT pathway." (PMID 35320976, 2022). "Notably, TRAIP activated the AKT pathway by promoting KANK1 polyubiquitination and degradation and downregulating IGFBP3 in osteosarcoma cells." (PMID 34349117, 2021). "We also found that KANK1 downregulated IGFBP3 in osteosarcoma cells." (PMID 34349117, 2021). "Thus, the KANK1/IGFBP3/AKT pathway is crucial for understanding the specific mechanism of the progression of osteosarcoma." (PMID 34349117, 2021). "Moreover, IGFBP3 was also found to inhibit the osteosarcoma cell migration via attenuating the PI3K/AKT/VCAM-1 signaling." (PMID 34349117, 2021). "We also found that TRAIP regulated IGFBP3 expression through KANK1 in osteosarcoma cells." (PMID 34349117, 2021). "It has been reported that IGFBP3 could diminished the activation of AKT induced by TGF-β1 in osteosarcoma cells and block cell proliferation and cell cycle progression." (PMID 34349117, 2021). "Besides, circ_0000285 could promote proliferation, migration, invasion and inhibit apoptosis of osteosarcoma by miR-409-3p/IGFBP3 axis." (PMID 33041662, 2020). "Another study showed that IGFBP-3 induced the expression of VCAM-1 and mediates the migration of human osteosarcoma cells through the activation of PI3K, Akt, and AP-1 signaling pathways." (PMID 36713521, 2022). "The other target gene of miR-153, TGFβ, is up-regulated in cancer cells such as osteosarcoma, resulting in overexpression of p-SMAD2, p-SMAD3, EGFR, IGF binding protein-3 (IGFBP-3) which are the crucial proteins in downstream of TGFβ signaling pathway." (PMID 36158686, 2022). "Conversely, KANK1 overexpression upregulated IGFBP3 and reduced AKT phosphorylation levels in osteosarcoma cells." (PMID 34349117, 2021). "The patients with metastatic (5.51 ± 0.57) and recurrent (5.64 ± 0.66) osteosarcoma tumors showed higher level of IGFBP-3 in the serum compared to non-metastatic (3.91 ± 0.20) (P=0.001) and non-recurrent (3.93 ± 0.18) (P=0.001) osteosarcoma tumors." (PMID 36713521, 2022). "In addition, we found that TRAIP promoted KANK1 polyubiquitination and subsequent degradation, downregulating IGFBP3 and activating the AKT pathway in osteosarcoma cells." (PMID 34349117, 2021).
osteosarcoma (continued). "In a retrospective study of 37 patients, it was found that circulating levels of IGF-1 and IGFBP-3 were not predictive of the development or clinical characteristics of pediatric osteosarcoma." (PMID 22587902, 2012). "This study aimed to evaluate the toxicity of GO on osteosarcoma in vitro using tumor cell lines with and without knocking out the IGF and IGFBP3 genes." (PMID 32742448, 2020).
clear cell renal cell carcinoma (10 papers, 2018 to 2024). "Microarray analysis showed increased IGFBP-3 mRNA in 63% of clear cell renal cell carcinomas and the higher IGFBP-3 staining intensity in high grade (Fuhrman grades 3 and 4) clear cell renal cell carcinomas." (PMID 35328822, 2022). "It is known that IGFBP3 can be considered as one of the potential markers of ccRCC, a significant increase of its expression is found in clear cell renal cancer." (PMID 31936274, 2020). "IGFBP3 expression has been reported to be increased in head and neck squamous cell carcinomas as well as renal clear cell carcinoma." (PMID 29947889, 2018). "For example, IGFBP-3 is highly overexpressed in the cytoplasm of high-grade clear cell renal cell carcinomas compared to low-grade or normal kidney." (PMID 29623068, 2018). "A cell line derived from metastatic clear cell renal cell carcinoma highly expresses IGFBP3 and IGF-1 compared to normal proximal tubule cell, and the autocrine actions of IGF-1 and IGFBP3 promote and inhibit cell proliferation, respectively." (PMID 35370981, 2022).
coronary artery disease (10 papers, 2015 to 2025). "Consistently, an observational study indicated that low circulating IGF-1 and high IGFBP-3 levels were significantly associated with increasing the risk of developing ischemic heart disease in a primary prevention population." (PMID 35332212, 2022). "High circulating IGFBP-3 concentration predicts greater incidence of cardiovascular conditions including ischemic heart disease and congestive heart failure and high risk of cancer." (PMID 32410992, 2020). "The IGFBP‐3‐increasing allele of SNP rs646776 (CELSR2 locus) was associated with increased risk of coronary artery disease (P = 9.4 × 10−15)." (PMID 27329260, 2016). "Moreover, reduced levels of IGFBP3 are associated with an increased risk of cardiovascular disease, including coronary artery disease and cardiovascular disease mortality." (PMID 38920980, 2024). "In a small clinical study, serum concentration of IGFBP3 was significantly correlated with coronary arteriosclerosis." (PMID 39526184, 2024).
Hyperinsulinemia (10 papers, 2012 to 2023). An increased concentration of insulin in the blood. "Acute hyperinsulinemia due to consumption of high glycemic load diet would cause an increase in IGF-1/insulin-like growth factor binding protein-3 (IGFBP-3) ratio, thus enhancing the effects of IGF-1." (PMID 22898209, 2012). "We thought that in well-growing SGA infants, IR leads to compensatory hyperinsulinemia which in turn increases circulating IGF-1 and possibly IGFBP-3 levels." (PMID 23748063, 2013). "Hyperinsulinemia elevates serum concentrations of free insulin-like growth factor-1 (IGF-1) and androgens, while simultaneously reducing insulin-like growth factor-binding protein 3 (IGFBP-3) and sex hormone-binding globulin." (PMID 36964104, 2023).
atherosclerosis (9 papers, 2013 to 2024). A disease characterized by the build-up of fatty material and calcium deposition in the arterial wall resulting in partial or complete occlusion of the arterial lumen. "In NAFLD, IGFBP3 levels are believed to be reduced, while elevated IGFBP3 levels correlate with atherosclerosis." (PMID 38034020, 2023). "IGFBP3 is involved in oxidative stress, atherosclerosis and left ventricular hypertrophy." (PMID 32682418, 2020). "Recent research suggests that IGFBP-3 secretion by senescent cells in the fibrous cap antagonizes IGF-I-mediated switching of VSMCs from a contractile to a promigratory state, leading to speculation that inhibiting IGFBP-3 action might be of therapeutic benefit in atherosclerosis." (PMID 39595651, 2024).
Cirrhosis (9 papers, 2014 to 2025). A chronic disorder of the liver in which liver tissue becomes scarred and is partially replaced by regenerative nodules and fibrotic tissue resulting in loss of liver function. "HCC was associated with a significant reduction in serum IGF-1 and IGFBP-3 levels compared to cirrhosis (p = 0.037)." (PMID 29113370, 2017). "In contrast, lower levels of IGFBP3 were associated with cirrhosis development." (PMID 34782638, 2021). "The serum IGF-I and IGFBP3 levels of the healthy group were significantly higher than those of the cirrhosis group (p < 0.01)." (PMID 29113370, 2017). "This is likely because of reduced secretion of the liver-derived factors IGF1 and IGFBP3 in cirrhosis and HCC patients with chronic liver damage and functional insufficiency." (PMID 29113370, 2017). "The geometric mean and standard deviation (SD) of serum IGF1 and IGFBP3 levels in the healthy, cirrhosis, and HCC groups were calculated." (PMID 29113370, 2017). "The geometric mean serum levels of IGF1 and IGFBP3 differed significantly among the healthy, cirrhosis, and HCC groups independently of the degree of impairment of liver function." (PMID 29113370, 2017). "Additionally, patients with cirrhosis had lower circulating IGF1 and IGFBP3 levels than healthy controls (p < 0.001)." (PMID 29113370, 2017).
Hepatic steatosis (9 papers, 2013 to 2024). Steatosis is a term used to denote lipid accumulation within hepatocytes. "We also revealed that a lower IGF-1/IGFBP-3 ratio might cause more advanced hepatic steatosis in patients with HCV-related CLD." (PMID 29342898, 2018). "In the present study, we have shown that long-term DHEA feeding reduced both serum IGF-1 and IGFBP-3 levels, which potentially can be effective in reducing liver steatosis." (PMID 28335515, 2017).
lymph node metastasis (9 papers, 2008 to 2025). "S100A10, S100A6, S100A4 and IGFBP3 have all been linked to PTC with lymph node metastasis (LNM)." (PMID 40430098, 2025). "Interestingly, the up-regulated IGFBP3 mRNA expression was significantly associated with OSCC patients with lymph node metastasis." (PMID 26540630, 2015). "In addition, there may be certain association between IGFBP-3 and lymph node metastasis (P=0.05), and BMI (P=0.06)." (PMID 18781172, 2008). "Nevertheless, lower IGFBP3 was significantly evident among patients with liver and lymph node metastasis and those with lymphovascular invasion in addition to patients with negative family history." (PMID 34858769, 2021). "Lower IGFBP3 was significantly evident among patients with liver and lymph node metastasis and those with lymphovascular invasion in addition to patients with positive family history." (PMID 34858769, 2021). "Lower IGFBP3 was significantly high among patients with liver and lymph node metastasis, lymphovenous invasion, and patients with positive family history." (PMID 34858769, 2021). "Because IGF1R status is deeply associated with IGF1R and IGFBP3 status, multivariate analysis was performed with two factors: IGF1R-positive and IGFBP3-negative expression, and lymph node metastasis." (PMID 23962053, 2013). "Importantly, 30 and 40% of the animals had lymph node metastasis after orthotopic injection of LN1–1 IGFBP3 sh4 (n = 9) and sh5 (n = 10) while 70% of the animals with lymph node metastasis after injection of LN1–1 cells expressing the vector control." (PMID 26540630, 2015). "The expression of IGFBP3 was downregulated in 86 gastric adenocarcinomas tissues relative to their adjacent normal tissues, and low expression of IGFBP3 was also correlated with advanced lymph node metastasis, distant metastasis and poor overall survival." (PMID 24386080, 2013). "On univariate analysis, three factors, IGF1R overexpression, IGF1R-positive and IGFBP3-negative expression, and lymph node metastasis, were significantly associated with worse overall survival." (PMID 23962053, 2013). "IGFBP3 expression was significantly lower in gastric tumor with lymph node metastasis (p=0.045)." (PMID 24386080, 2013). "Therefore, we not only identified a new therapeutic biomarker for CC patients with lymph node metastasis but also provided a novel regulatory molecular mechanism involving cholesterol reprogramming and PDGF-AA/IGFBP-3 secretion." (PMID 35597782, 2022). "The IGFBP-3 expression level was significantly higher in patients with favorable prognostic factors, including earlier T category (P = 0.030), the absence of lymph node metastasis (P = 0.021), and distant metastasis (P = 0.006)." (PMID 26370590, 2015). "Again, 37.5 and 42.9% of the experimental animals developed lymph node metastasis after orthotopic injection of OEC-M1 IGFBP3 (n = 8) and IGFBP3 GGG (n = 8) while 12.5% of the animals with lymph node metastasis after injection of OEC-M1 cells expressing the vector control (OEC-M1 PB)." (PMID 26540630, 2015). "The multivariate survival analysis indicated that IGF1R-positive and IGFBP3-negative expression, along with lymph node metastasis, were independent prognostic indicators." (PMID 23962053, 2013). "IGF1R-positive and IGFBP3-negative expression and lymph node metastasis were independent predictors of poor prognosis." (PMID 23962053, 2013). "In addition, patients with lymph node metastasis absent had elevated serum IGFBP‐3 levels than those of patients with lymph node metastasis present (4.73 [3.92, 5.72] vs 4.11 [2.45, 4.83] μg/mL, P = 0.02)." (PMID 31218761, 2019). "By ELISA, we found that IGFBP3 protein could be detected in plasma of OSCC patients as shown in the previous studies, however, the level of IGFBP3 protein did not demonstrate any difference between OSCC with or without lymph node metastasis." (PMID 26540630, 2015).
lymph node metastasis (continued). "Given that IGFBP3 is a secretary protein, we considered whether IGFBP3 protein could be measured in the plasma of OSCC patients and used to differentiate the status of lymph node metastasis." (PMID 26540630, 2015). "Moreover, IGFBP3 expression was significantly lower in gastric tumor with lymph node metastasis compared with that without lymph node metastasis (p=0.045)." (PMID 24386080, 2013).
nasopharyngeal carcinoma (9 papers, 2020 to 2024). A carcinoma arising from the nasopharyngeal epithelium. "On the contrary, IGFBP3 is abundantly expressed in nasopharyngeal carcinoma and is associated with poor prospects and tumor metastasis." (PMID 38326861, 2024). "For example, IGFBP3 expression was increased in nasopharyngeal carcinoma and IGFBP3 was also associated with cell migration and adhesion." (PMID 33041662, 2020). "However, IGFBP-3 overexpression has been associated with the progression and metastasis of several cancer types, including cutaneous squamous cell carcinoma and nasopharyngeal carcinoma." (PMID 35356065, 2022). "IGFBP3 is abundantly expressed in nasopharyngeal cancer tissues, which correlates with poor prognosis and tumor metastasis." (PMID 35966888, 2022). "Another illustration of IGFBP-3 acting as an oncogene relates to the circRNA, circ-0046263, which is upregulated in nasopharyngeal carcinoma (NPC), with highest expression in metastatic disease." (PMID 35597813, 2022). "EMT has been classically associated with increased invasive activity of tumor cells, and indeed, IGFBP‐3 induced migration of tumor cells in nasopharyngeal carcinoma and squamous cell carcinoma." (PMID 32767843, 2020).